RNU7-56P (RNA, U7 small nuclear 56 pseudogene)
Synonyms: U7.56
Gene: Small nuclear RNA gene on chromosome X (16,767,844 to 16,767,905, forward strand). Ensembl gene ENSG00000238709.
Homologues: Orthologues: macaque U7 (98% identical). Paralogues in human: RNU7-52P (87% identical), RNU7-8P (87% identical), RNU7-12P (85% identical), RNU7-13P (85% identical), RNU7-2P (85% identical), RNU7-30P (85% identical), RNU7-65P (85% identical), U7 (85% identical), RNU7-160P (84% identical), RNU7-183P (84% identical), RNU7-23P (84% identical), RNU7-26P (84% identical), and 143 more.